CXCR3 (C-X-C motif chemokine receptor 3)
Diseases named in the same sentence as CXCR3 in open-access papers (continued):
Sharing a sentence is not in itself a finding about the gene and the disease.
tumor (continued). "To test whether enhanced CXCR3 expression is necessary for the rejection of MC38 tumors and extended survival observed in tumor-bearing ALK5ΔCD8 mice, we blocked CXCR3 in vivo with an anti-CXCR3 blocking antibody delivered on days 4, 8, and 12 after tumor challenge." (PMID 32273499, 2020). "However, the expression of CXCR3A, a splicing variant of CXCR3, has been reported to promote PC, whereas CXCR3B might be a tumor suppressor." (PMID 33195424, 2020). "However, its receptor CXCR3 is also overexpressed on MM cells and signaling through the receptor has been shown to promote chemotaxis and secretion of matrix metalloproteinases, which drive tumor invasion." (PMID 32355275, 2020). "Thus, IP-10 may be secreted by tumor cells in increasing amounts since expression of CXCR3 by T cells is reduced with asbestos exposure." (PMID 32977478, 2020). "Interestingly, and consistent with a role of these chemokines in tumor growth modulation, a critical role for their receptor CXCR3 has been identified by demonstration of enhanced tumor growth in CXCR3 KO mice with a syngeneic tumor model due to impaired CD8+ T cell migration." (PMID 33117369, 2020). "The increased production of IFN-γ by intratumoral lymphocytes could enhance the intratumoral expression of CXCL9 and CXCL10 and subsequent recruitment of the hetIL-15-expanded pool of circulating CXCR3+ lymphocytes, generating a positive amplification loop that limits tumor growth." (PMID 32461349, 2020). "Therefore, targeting PTPN2 may not only enhance the antigen‐specific activation and function of CAR T cells, but also limit “on‐target off‐tumour” toxicities by driving the homing of CXCR3‐expressing CAR T cells to CXCL9/10/11‐expressing tumours." (PMID 31803974, 2020). "From these results, high expression levels of NK cell-activating receptors, activated T cell markers (PD-1, CXCR3, and especially IFNγ), and tumor's T cell recruitment-associated markers (IFNγ receptor, PD-L1, and CXCL9) were necessary for successful T cell infiltration and tumor killing." (PMID 32795913, 2020). "Loss of CXCR3 also did not impact the activation and expansion of tumor-infiltrating T cells." (PMID 31775909, 2019). "Thus, blocking CXCR3 on tumor cells might also impair the ability of CXCR3+ NK and T cells to efficiently kill tumor cells." (PMID 30319622, 2018). "Thus, results suggest that changes in the ratio of the CXCR3 variants is associated to neoplastic transformation and tumor growth rather than tumor metastasis." (PMID 29416784, 2018). "Likewise, the expression of CXCR3 by lymphocytes can mediate its migration to GBC tumor beds." (PMID 29600445, 2018). "In addition, A. muciniphila can also increase the patient’s response to drugs by increasing the recruitment of CCR9+ CXCR3+ CD4+ T lymphocytes during the immunotherapy of tumor patients with PD-1/PD-L1 and increase the progression-free survival (PFS) of patients after treatment." (PMID 30687277, 2018). "Consequently, it is still unclear whether the CXCR3 immune infiltrate in human SCC and BCC is associated with tumor regression or progression." (PMID 30320116, 2018). "Thus, CXCL10 expression may lead to rapid tumor rejection by recruitment of CXCR3+ T-cells into the nascent tumor, in analogy to immune-competent mice implanted sub-cutaneously with CT26 cells, treated with an CXCL10-CXCL11 fusion chemokine." (PMID 29163806, 2017). "Thus, we propose that CXCR3 plays varied roles in the immune response to cancer at various stages of tumor dissemination and development, and pan inhibitors of CXCR3 signaling could have pleotropic effects." (PMID 28358049, 2017). "Furthermore, CTLs directed to tumor-associated antigens survivin2B and PBF could be induced from CD8+CD73+CD45RA+CD62L+CXCR3+ cells of HLA-A*24:02+ cancer patients." (PMID 27471640, 2016).
tumor (continued). "In mouse, in accordance with higher and preferential expression levels of CXCR3, the NK cell population mostly affected by CXCR3 function is the CD27high subset that colonizes draining LN following DC vaccination, cowpox virus infection, and during tumor growth." (PMID 27766097, 2016). "Furthermore, we found that IP-10 and CXCR3 levels in human PDAC correlated with higher tumor desmoplasia, suggesting that IP-10 expression may depend on the presence of PSCs in the tumor microenvironment similar to our in vitro model." (PMID 25415223, 2014). "Finally, we examined the presence of chemokines signaling through CCR4 and CXCR3 in protein extracts from tumor and unaffected tissue to investigate if differences in chemokine production could explain the altered T cell recruitment to tumor tissues." (PMID 22319577, 2012). "This is consistent with CXCR3’s established role in guiding T cell trafficking and with CXCR3+ T cells being recruited to CXCL10-rich tumor sites to augment antitumor immunity." (PMID 41129238, 2026). "CXCR3 signaling is critical for DOT-cell migration in vitro and in vivo, as pharmacologic blockade reduced tumor homing, whereas enhancing CXCR3 ligand expression increased DOT-cell infiltration and improved tumor control." (PMID 42208977, 2026). "CXCR3, a common receptor for CXCL9 and CXCL10 recruits Th1 cells to the TME, suppressing tumour growth." (PMID 40852716, 2025). "MSC-derived chemokines CXCL9, CXCL10, and CCL5 interact with CXCR3 and CCR5 on NK cells to promote their directed migration into tumor tissues." (PMID 40643499, 2025). "These chemokines promote CXCR3-dependent immune cell recruitment, establishing a positive feedback loop that amplifies CAR-T cell tumor infiltration and enhances the overall anti-tumor immune response." (PMID 40433363, 2025). "The STAT1-IFNγ regulatory axis has been reported to enhance anti-tumor immunity by recruiting CXCR3+CD8+ T cells and CXCR3+ NK cells." (PMID 40346580, 2025). "This CXCL10 surge correlated with extravasation of CXCR3+CD8+ T cells, leading to greater tumor shrinkage and improved survival." (PMID 40311102, 2025). "In cancer cells, autocrine CXCR3 signaling promotes metastasis and growth through AKT signaling, while CXCL9 and CXCL11 can inhibit tumor growth by facilitating immune cell infiltration." (PMID 39940842, 2025). "IHC analysis supported the dual inhibition of FGFR4 and CXCR3, which reduced the number of α-SMA- and Ki-67-positive cells within the TME, suggesting attenuation of CAF differentiation and tumor proliferation." (PMID 40447617, 2025). "NicheNet indicated that tumor‐derived chemokines (CCL5, TGFB1) interacted with Tregs receptors (CCR4, CCR5, CXCR3), promoting the Treg recruitment." (PMID 41028931, 2025). "Then, it is revealed that Plac1+ tumor cells recruit CD4+ T cells via CXCL11/CXCR3 and induce Treg differentiation via PVR/TIGIT, which in turn activates the tumorigenic signaling of Plac1+ tumor cells via LTA/LTBR and forms a reciprocal protumor loop." (PMID 40056047, 2025). "CXCR3, a chemokine receptor, plays a crucial role in the trafficking and retention of effector T cells, including TRM cells, to tumor sites." (PMID 40066439, 2025). "These chemokines create a gradient that guides CXCR3-expressing immune cells, such as activated CD8+ T cells and natural killer (NK) cells, toward the tumor site." (PMID 41041322, 2025). "Ablation of both CXCR3 isoforms significantly impaired GBM cell proliferation, migration, and tumor growth both in vitro and in immunodeficient mice." (PMID 40185710, 2025). "When interacting with CXCR3, CXCL9 promotes tumor growth and metastasis in certain contexts, but it also recruits immune cells like cytotoxic T-cells to the tumor, supporting anti-tumor immunity." (PMID 40362215, 2025).
tumor (continued). "In the meantime, Plac1+ tumor cells shape a Treg‐related immunosuppressive microenvironment via CXCL11/CXCR3 and PVR/TIGIT, which in turn activates the tumorigenic signaling of Plac1+ tumor cells via LTA/LTBR and forms a reciprocal protumor loop." (PMID 40056047, 2025). "CXCL10 and CCL5 bind to CXCR3 (chemokine (C-X-C motif) receptor 3) and CCR5 receptors located on tumor cells." (PMID 41471830, 2025). "Another approach is enhancing macrophage homing to tumours by upregulating chemokine receptors like CCR2 or CXCR3, which can significantly improve CAR-M migration and retention at tumour sites, thereby boosting therapeutic efficacy." (PMID 40624498, 2025). "To summarize our findings concisely: we have uncovered a novel mechanism through which PRMT5 promotes tumor growth, namely by regulating CXCL10 expression within tumor cells while facilitating recruitment of T cells via interaction between CXCL10 and CXCR3." (PMID 41463372, 2025). "In L-TTF2 patients, circulating CXCR3+CD8+-T-cells were still elevated after failure of first-line CTX, mirroring the immune-enriched nature of the treatment-naïve tumor tissues with e.g., cytotoxic CXCR3+CD8+-T-cell infiltration." (PMID 40696453, 2025). "We provide evidence in both mice and humans that the coordinated expression of CXCR3, CCR5, and CXCR6 defines distinct CD8+ T-cell subsets with divergent roles in mediating tumor clearance and immune-related toxicity following dual checkpoint blockade." (PMID 41415437, 2025). "However, targeting CXCR3 may also impair the migration of antitumor immune cells to the tumor site." (PMID 41041322, 2025). "In this study, we described the role and molecular mechanism of oHSV in inducing TLS formation in tumours, and identified that oHSV therapy recruits stem‐like TCF1+CD8+ T cells via CXCL10/CXCR3 pathway to propagated TLS formation." (PMID 39219056, 2025). "The expanded NK cells express the chemokine receptors CXCR3, CCR5, and CXCR6, and the lung of tumor-resected mice express mRNA of the corresponding ligands CXCL9/10/11, CCL3/4/5, and CXCL16." (PMID 39835538, 2025). "Our study demonstrated similar results, CXCR3 knockdowns inhibited CRC cell migration, while CXCR3 inhibitors diminished CD8+ T cell infiltration and facilitated tumor metastasis." (PMID 40651961, 2025). "The EOMES GRN, encompassing CD8A, GZMK, STAT5A, CXCR3, and LAG3, integrates cytotoxic effector functions, migratory capacity, and checkpoint regulation—features critical for sustained anti-tumor immunity." (PMID 40520886, 2025). "MSC-sourced CXCL10 (IP-10) facilitates NK cell recruitment into the tumor microenvironment and supports NKG2D expression through CXCR3-mediated activation." (PMID 40643499, 2025). "TGF‐β suppresses chemokine receptor CXCR3 transcription by SMAD2/3 and thereby limiting CD8+ T‐cell trafficking to the tumor." (PMID 39083441, 2025). "CXCR3, the cognate receptor for CXCL9, −10, −11, is predominantly expressed on monocytes as well as T, natural killer (NK), dendritic, and tumor cells." (PMID 40447617, 2025). "Effector T cells primed in the spleen by the combination therapy migrates to the tumor site via chemokine‐guided trafficking mechanisms involving CXCR3 and CXCL10 in the tumor microenvironment." (PMID 40498983, 2025). "Their findings confirmed that CXCR3, CXCR2, and CXCR6 are prognostic genes related to AML and its tumor immune microenvironment, offering new insights into AML prevention and treatment." (PMID 40427609, 2025). "Flow cytometric analysis of tumor-infiltrating lymphocytes indicated a reduction in the number of infiltrating CD3, CD8, and CD4 T lymphocytes in the MEKi+RT+anti-CXCR3 group compared to the MEKi+RT+isotype group." (PMID 41368644, 2025). "This conclusion is also supported by a corresponding increase in the ligands for CXCR3, CCR5 (e.g., CXCL9, CXCL10, CCL5) in both tumor and liver supernatants after treatment, whereas CXCR6 ligand (CXCL16) is higher only in the tumor." (PMID 41415437, 2025).
tumor (continued). "The chemokine receptor CXCR3, induced by IFN, promotes the migration of T-cells into inflammatory sites and the tumor microenvironment." (PMID 39722065, 2025). "Within the NKim subcluster, gene expression of key receptors and cytokines (Il15, CXCR3, KLRG1) correlated significantly with tumor grade." (PMID 40821787, 2025). "For instance, CXCR3, a receptor for chemokines CXCL9, CXCL10, and CXCL11, is more highly expressed in tumor tissues than in normal tissues." (PMID 39940842, 2025). "Key chemokines involved in CD8+ T cell recruitment (CCR3, CXCL10, CXCL9) and their receptors (CCR2, CCR5, CXCR3) were consistently downregulated in FAM174B-high tumors, potentially limiting effector immune cell trafficking to the tumor microenvironment." (PMID 40959568, 2025). "For example, the co-expression of IL-15 and IL-21 enhances survival, proliferation, and functionality, while engineering these cells to express chemokine receptors such as CXCR3 and CCR5 improves their tumour-homing ability." (PMID 40624498, 2025). "To further examine the role of extracellular miR-762 in the OSCC tumor microenvironment, we applied an OSCC-conditioned medium to Jurkat cells to assess CXCR3 expression." (PMID 39940842, 2025). "Elevated expression of Cxcr3 and Cxcl10 is compatible with chemokines mediating enhanced CTL recruitment from secondary lymphoid tissues to the tumor site." (PMID 40498983, 2025). "Initially TNF-γ works by recruiting cohorts (CXCL9, CXCL10, CXCL11, and CXCR3) to promote antigen presentation (MHC class I and class II), T-cell initiation and activation (CD80, CD86, and CD40), and tumor cell killing (Fas and FASL)." (PMID 39835116, 2024). "In brief, chemokine signaling is crucial for tumor angiogenesis (CXCR2 and CXCR4), immunosuppression (CXCR3 and CCR2), and tumor progression and metastasis (CCR5 and CXCR6)." (PMID 39456552, 2024). "For example, CXCR3, when expressed by CD8+ T cells, allows their ligands CXCL9 and CXCL10 to guide the migration of CD8+ T cells to tumor tissue, resulting in an anti-tumor effect." (PMID 39769501, 2024). "The CXCR3/CXCL10 axis has been known for its pro-metastatic potential and is highly expressed in several tumour types." (PMID 39146303, 2024). "NRTUA treatment altered IL-12, IFN-γ, and the CXCR3-stimulating cytokine-involved CD8+ T-cell population in the tumor microenvironment (TME), subsequently inhibiting melanoma tumor growth in mice." (PMID 38297164, 2024). "Chemokines can serve pro- or anti-tumor functions, with the chemokines CXCL9 and CXCL10, ligands for CXCR3, being of the most interest in the anti-tumor category due to their ability to attract effector CD8+ and CD4+ T cells." (PMID 38803496, 2024). "We thus demonstrated a possible interaction of CXCR3 expressed by activated T cells and CXCL10 secreted by tumor cells." (PMID 38495500, 2024). "IFNα specifically mediated CXCL10 expression in both tumor cells and PBMCs to recruit and activate CD8+ T cells, which expresses CXCR3 abundantly." (PMID 38953994, 2024). "In conclusion, CXCL10, which directly polarizes and potentiates CXCR3+ CD8+ T cells, also directly potentiates these cells to limit tumor growth." (PMID 39474427, 2024). "We found clues in the elevated expression of key chemokine receptors, specifically CXCR3 and CCR5, which facilitate tumor infiltration." (PMID 39763661, 2024). "CXCR3 activation mediates the interaction between CD8+ T LFA-1 and tumor ICAM-1, further promoting T cell adhesion and activation within the tumor microenvironment." (PMID 38953994, 2024). "Another approach to recruiting T cells into tumor is to use constructs expressing a chemokine receptor, such as CCR2, CCR2b, CXCR3, CCR4, CCR7, CXCR2, or CXCR4, which can interact with the relevant tumor-derived chemokine." (PMID 38927974, 2024). "Another important chemotactic NK cell receptor is CXCR3, which binds to the IFN-γ-induced and tumor-secreted CXCL9, CXCL10, and CXCL11 chemokines." (PMID 39339180, 2024).
tumor (continued). "Activation of the CXCL11/CXCR3-axis in CD8+ T cells significantly increased apoptosis of cancer cells and reduced tumor growth both in in vitro and in vivo." (PMID 39543650, 2024). "Third, AA additionally inhibits the expression of genes coding for chemokine and cytokine receptors essential for anti-tumor NK cell functions, notably CX3CR1 and CXCR3, which are similarly downregulated in TANK compared to normal NK cells." (PMID 39563446, 2024). "Next, the specific CXCL10 receptor CXCR3 (CD183) involved in NK and T lymphocyte migration was detected in the PBMCs and tumor cells to validate the abundant expression characteristic of CXCR3 in T lymphocytes." (PMID 38953994, 2024). "In pre-clinical studies, CD206 TAMs were found to be the primary source of CXCL9—the well-established chemoattractant for CXCR3-expessing NK and CD8 T cells, driving anti-tumor immunity." (PMID 38893266, 2024). "Through its interaction with the receptor CXCR3, CXCL9 affects the behavior of various immune cells within the tumor, particularly T cells and NK cells." (PMID 38791448, 2024). "At the same time, we found fewer tumour-specific CD8+ T-cells in the lungs, and lower expression of the activation marker CD43 and GzmB in CD8+ T-cells in the tumour when CXCR3 was blocked compared to untreated IAV infected tumour bearing mice." (PMID 38271469, 2024). "Particularly, we found that CD8+ T lymphocytes abundantly expressed CXCR3, a receptor of CXCL10, by flow cytometry, indicating that tumor-intrinsic CXCL10 potentially recruited CD8+ T in tumor microenvironment." (PMID 38953994, 2024). "Mice were implanted with KPC-derived tumor cells on a single flank, and then treated with a STING agonist, which significantly reduced the tumor burden, increased the CD8+/CD4+ T-cell ratio, and increased CXCR3+ CD8+ T cells in the PDAC TME." (PMID 38339310, 2024). "IRF1 increased CXCL10 gene transcription and exhibited antiproliferative and pro-apoptotic effects on tumor cells, presumably by activating the CXCL10/CXCR3 autocrine pathway." (PMID 38396830, 2024). "This suggests that CD8+ T cells infiltrate the tumor via the CXCL9/CXCL10-CXCR3 pathway and therefore T cell expression of CXCR3 is cruicial for their migration toward CXCL9/10 produced by TAMs." (PMID 38533720, 2024). "Through binding to its unique receptor, CXC chemokine receptor 3 (CXCR3), CXCL10 exhibits pleiotropic functions in tumor biology." (PMID 38720149, 2024). "Our findings also highlight the critical role of CXCR3 in the recruitment and activation of CD8+ T cells within the tumor microenvironment and its potential implications for immunotherapeutic efficacy." (PMID 38953994, 2024). "For instance, CCR4/5 and CXCR3, expressed by CD8+ T cells, allow their ligands CCL5, CXCL9, and CXCL10 to guide the migration of CD8+ T cells into tumor tissue." (PMID 39769501, 2024). "Further research is needed to unravel the interplay between the CXCR3/CXCL10 axis, the metastatic niche as well as the tumour cell." (PMID 39146303, 2024). "In cancer cells, the binding of CXCL11 to CXCR3 enhances EMT and cancer stemness, promoting tumor progression." (PMID 39543650, 2024). "In vivo PET imaging of MC38 tumor bearing mice before, during and after ICI using [64Cu]Cu-NOTA-α-CXCR3 (Kd = 3.3 nM) revealed a strong dependence of CXCR3-specificity of tracer accumulation in secondary lymphoid organs on molar activity." (PMID 39196448, 2024). "Results from a panel of in vivo and ex vivo 3D tumor models imply that, beyond driving CD8+ T cells into T-cell exhaustion, a major role of PD-1 and CTLA-4 is in limiting the CXCR3-based self-feeding mechanism of T cell potentiation." (PMID 39474427, 2024). "CD4+ Th1-polarized effector memory cells expressing CXCR3 and CCR5, the receptors for CXCL9/10/11 and CCL5, respectively, are another significant component of tumor-infiltrating lymphocytes (TILs)." (PMID 39114657, 2024).